VIP (vasoactive intestinal peptide)
Diseases named in the same sentence as VIP in open-access papers (continued):
Sharing a sentence is not in itself a finding about the gene and the disease.
depression (18 papers, 2013 to 2026). "Beyond SCZ, dysregulation of PVALB-, SST-, and VIP-expressing interneurons has been implicated in a range of neuropsychiatric and neurodegenerative conditions including bipolar disorder, major depression, autism spectrum disorder, and Alzheimer’s disease." (PMID 41159096, 2026). "Inhibitory VIP+ neurons were associated with depression, further confirming GABAergic dysregulation in major depressive disorder, and as expected, microglia were positively associated with Alzheimer’s disease." (PMID 40791449, 2025). "Second, we investigated the relative intrinsic VIP-associated strength of connectivity between the selected regions of the network in our participant group while controlling for anxiety and depression (unthresholded) (right)." (PMID 33446759, 2021). "Functional and structural magnetic resonance imaging were used to evaluate functional connectivity and brain volume respectively, and their associations with VIP concentrations within brain regions associated with anxiety and depression." (PMID 33446759, 2021). "Vasoactive intestinal polypeptide (VIP) is a neuroendocrine peptide distributed throughout the human body, including the CNS, where it is particularly abundant in brain regions associated with anxiety and depression." (PMID 33446759, 2021). "In conclusion, we found that VIP plasma levels were positively associated with brain function and volume in regions associated with emotional processing, and inversely related to symptoms of anxiety and depression in healthy females." (PMID 33446759, 2021). "Our interest herein was to investigate central processing associated with VIP in healthy females through potential associations with symptoms of anxiety and depression, as well as brain structure and function within anatomically connected regions involved in emotional processing." (PMID 33446759, 2021). "VIP is a neuroendocrine peptide distributed throughout the human body, including the central nervous system (CNS), where it is particularly abundant in brain regions associated with emotional processing, specifically anxiety and depression." (PMID 33446759, 2021). "Decreased VIP levels have been found in patients with major depression, which has also been found in PD patients." (PMID 34566619, 2021). "Results from the regression analysis with bootstrapping controlling for age, anxiety, depression, and total intracranial volume, showed VIP concentrations significantly positively correlated with brain volume in the left amygdala (r = 0.28, p = 0.007) and left lateral OFC (r = 0.29, p = 0.004)." (PMID 33446759, 2021). "Plasma VIP concentrations and anxiety/depression symptoms were measured in 37 healthy females." (PMID 33446759, 2021). "Moreover, the lower VIP levels are consistent with reduced parasympathetic tone that has been reported in depression, considering VIP levels probably involved in the pathobiology of affective disorders." (PMID 34566619, 2021). "There was a significant negative association between VIP and anxiety (r = − 0.44, p = 0.002) and depression (r = − 0.50, p = 0.001), respectively." (PMID 33446759, 2021). "Our findings provide important further evidence on psychological, functional, and structural levels to support VIP as a potential target for therapeutic investigation in anxiety and depression, and in disorders of the gut-brain axis with high psychological comorbidities." (PMID 33446759, 2021). "VIP has lateralized effects on the modulation of exploratory behavior and passive avoidance learning and anxiolytic and anti-depressive effects, and rescues deficits in hippocampal-dependent passive avoidance learning tasks in a rat model of depression." (PMID 32595454, 2020).
depression (continued). "The intimate hippocampal-olfactory bulb connection was further appreciated in depression models of bulbectomized mice, whereby depressive symptoms were alleviated when administering vasoactive intestinal peptide (VIP), a neurotransmitter, into area CA1, which is directly connected to the bulb." (PMID 27082425, 2016). "The PACAP system, in turn, is involved in the molecular pathways of the three main theories of depression (monoamine, neurotrophic, and endocrine), while VIP is shown to be aberrantly expressed in patients with IBS and has been hypothesized to be involved in its development." (PMID 36685848, 2022). "Reducing VIP activity can therefore be expected to shift the SST population as a whole towards sensitization, thereby driving PCs towards depression." (PMID 35210417, 2022). "Studies have shown that 5-HT, VIP and CHAT plays the important role on inducing diarrhea, high visceral sensitivity, and depression on IBS-D of patients and rats." (PMID 32982718, 2020). "Negative correlations were found between VIP levels and symptoms of anxiety (r = − 0.44, p = 0.002) and depression (r = − 0.50, p = 0.001)." (PMID 33446759, 2021). "There was a significantly greater increase in the levels of protein expression of SS and VIP in the blood and colonic mucosa of the patients with IBS-D with anxiety and depression, in comparison with those with IBS-D and normal anxiety and depression ratings (P<0.05)." (PMID 24137253, 2013). "Significant differences were observed between the numbers of SS+ and VIP+ cells in the colonic mucosa of the patients in the IBS-C group with anxiety and depression, in comparison with the numbers in the patients in the IBS-C group with normal anxiety and depression ratings (P<0.05)." (PMID 24137253, 2013). "Additionally, we found that lower serum VIP levels were detected in the anxiety subgroup and depression subgroup than in the non-anxiety subgroup and non-depression subgroup [(107.45 ± 15.40) pg/ml vs. (116.41 ± 13.67) pg/ml, P < 0.05]; [(104.45 ± 15.26) pg/ml vs. (113.43 ± 14.52) pg/ml, P < 0.05]." (PMID 34566619, 2021). "Patients with IBS-C in anxiety and depressive states expressed significantly higher levels of SS and VIP in the serum and colonic mucosa than IBS-C patients with normal anxiety and depression ratings (P<0.05)." (PMID 24137253, 2013).
breast carcinoma (17 papers, 2011 to 2024). "Adding vasoactive intestinal peptide to breast cancer cells stimulates EGFR and HER2 tyrosine phosphorylation." (PMID 37508387, 2023). "We found that silencing of VIPR2 in MDA-MB-231 and MCF-7 human breast cancer cells inhibited VIP-induced cell migration." (PMID 36237322, 2022). "In breast cancer, VIP or VPAC1 receptor antagonists can enhance the killing ability of chemotherapy on breast cancer cells." (PMID 36157238, 2022). "Breast cancer has been reported to express different types of peptide receptors, such as somatostatin, vasoactive intestinal peptide (VIP), gastrin-releasing peptide (GRP), and Y1R." (PMID 34421823, 2021). "18F(Arg15, 21)VIP localized to T47D breast cancer cells in nude mice and 64Cu-TP3982 localized to mammary tumors in MMTVneu transgenic mice." (PMID 30008698, 2018). "Increasing evidence shows that vasoactive intestinal peptide (VIP) in BIOCARTA_VIP_PATHWAY is highly expressed in breast cancer cells along with its receptor, and VIP-targeted nanomedicine is under study as therapy for breast cancer." (PMID 25233347, 2014). "VIP functions as an autocrine growth factor and regulates proliferation, survival, and differentiation in human breast cancer cells; it has proangiogenic functions in breast cancer." (PMID 22140573, 2011). "VIP interacts with VPAC1 in breast cancer cells, activating Gs." (PMID 37508387, 2023). "VIP addition to breast cancer cells increased EGFR and HER2 phosphorylation." (PMID 30008698, 2018). "However, in a PET imaging study of an F-18 labeled VIP analogue (Arg15, Arg21) VIP on T-47D nude mice model of human breast cancer, despite the T/M was as high as 3.4, the T/B was only 0.94." (PMID 24459669, 2013). "In addition, there are numerous evidences that (VIP) and its receptors, which are highly expressed in breast tumor cells, play an important role in the pathogenesis of breast cancer." (PMID 22140573, 2011). "Furthermore, these micelles were surface-functionalized with VIP to target breast cancer cells." (PMID 34959321, 2021). "This is consistent with VIP and its VPAC receptors being upregulated in various tumors, including HCC, pancreas, lung, breast cancers, and glioma." (PMID 39457515, 2024). "For example, some studies indicated that VIP/VIPR1 signaling stimulates transactivation of HER2 and EGFR in human breast cancer." (PMID 35864952, 2022). "The current study thus explores the effect of inhibiting VIP signaling with/without checkpoint inhibitors in murine breast cancer model." (PMID 30400835, 2018). "For example, cancers of the breast, endometrium, prostate, testis, urothelium/bladder, and melanoma showed an expression of VPAC1 or VPAC2 despite lacking VIP expression." (PMID 37444395, 2023).
Alzheimer disease (16 papers, 2012 to 2026). A progressive, neurodegenerative disease characterized by loss of function and death of nerve cells in several areas of the brain leading to loss of cognitive function such as memory and language. "In this context, single nucleotide polymorphisms in the 3′UTR region of type 1 receptor (VPAC-1) for vasoactive intestinal peptide (VIP) have been reported to be associated with some immune-mediated as well as with neurodegenerative diseases such as Alzheimer's Disease (AD)." (PMID 25390694, 2014). "VIP displays neuroprotective, anti-inflammatory, and immunomodulatory effects, making it promising for conditions such as Parkinson’s, Alzheimer’s disease (AD), and autism spectrum disorders, as well as brain injuries." (PMID 40001527, 2025). "The modulation of microglial activation, phagocytosis, and secretion by VIP is a promising therapeutic option for the treatment of Alzheimer's disease(AD)." (PMID 22328918, 2012). "The structurally related peptide VIP also seems to target similar pathways in microglia, as demonstrated in an animal model of Alzheimer’s disease, where the authors showed that VIP inhibited inflammation by blocking the signalling of p38 MAPK, p42/p44 MAPK, and NF-κB intracellular cascades." (PMID 35563181, 2022). "We next determined whether VIP treatment could affect Aβ plaque formation and accumulation in a mouse model of Alzheimer's disease." (PMID 22328918, 2012). "Modulation of Aβ-induced microglia activation and microglial phenotype by delivery of VIP into the brain may be a novel approach for the treatment of Alzheimer's diseases." (PMID 22328918, 2012). "Further validation was performed in another expression profile of AD, GSE33000, and the result implied high sensitivity and specificity of DGKG, MAP3K7IP2, NFKBIE, VIP, and PCCB for diagnosing Alzheimer’s disease (combined AUC = 0.9388)." (PMID 36092935, 2022). "Interestingly, both VIP and SST were reported to exert protective effects in neurodegenerative diseases, including Alzheimer's disease and PD through inhibiting the microglial activation and expression of the cytotoxic mediators, such as TNF-α, IL-1β, and prostaglandin E2." (PMID 32410857, 2020).
inflammatory bowel disease (16 papers, 2015 to 2026). A spectrum of small and large bowel inflammatory diseases of unknown etiology. "On the other hand, VIP may cause migraine attacks and inflammatory bowel disease through vasodilation and degranulation of mast cells on the dura mater." (PMID 41473187, 2025). "Inflammatory bowel disease is a chronic gastrointestinal inflammatory disorder associated with changes in neuropeptide expression and function, including vasoactive intestinal peptide (VIP)." (PMID 25932952, 2015). "In some studies, VIP knockout mice were more susceptible to chemically-induced intestinal inflammation, and human inflammatory bowel disease (IBD) patients show a reduction in VIP positive nerves proximal to severe mucosal damage." (PMID 31849864, 2019). "The reduction in VIP levels is likely to be beneficial because elevated VIP is considered to be a biomarker for an aggravated state of colonic inflammatory conditions, as seen in inflammatory bowel disease (IBD)." (PMID 39339770, 2024). "Moreover, we have reported the association between low serum VIP concentration and increased disease severity in patients with early SpA, namely reduced functional status, bone edema in MRI, and a more intense inflammatory burden (anemia, psoriasis, inflammatory bowel disease, and enthesitis)." (PMID 35955723, 2022). "During inflammatory bowel disease (IBD), an increase or decrease in VIP was observed, depending on the study." (PMID 39064711, 2024). "Only two patients in our study had inflammatory bowel disease; a non-significant trend toward lower levels of VIP was observed in both (data not shown)." (PMID 25711477, 2015). "Intestinal sensory neurons release VIP, which directly engages VPAC2 receptors on Treg cells to induce PD‐1 expression and enhance suppressive activity, thereby suppressing autoimmune responses and offering potential therapeutic targets for inflammatory bowel disease (IBD)." (PMID 41583906, 2026).
neuroendocrine tumors (15 papers, 2012 to 2025). "Nocturnal diarrhea in the discussed patient thus strongly suggests secretory diarrhea, most likely as an adverse drug reaction, or caused by a neuroendocrine tumor producing a secretagogue, such as vasoactive intestinal polypeptide (VIP)." (PMID 33398457, 2021). "These neuroendocrine neoplasms autonomously secrete VIP which acts on intestinal epithelial cells to induce fluid and electrolyte secretion into the lumen." (PMID 41195063, 2025). "While common causes include microscopic colitis, bile acid diarrhoea, and laxative use, rarer aetiologies such as vasoactive intestinal peptide (VIP)–secreting neuroendocrine tumours (VIPomas) must be considered when standard investigations fail." (PMID 41195063, 2025). "VIPomas are a type of neuroendocrine tumor that independently produces vasoactive intestinal peptide (VIP)." (PMID 37895355, 2023). "Vasoactive intestinal peptide (VIP) secreting tumors (VIPomas) are insidious functional neuroendocrine tumors originating mainly from pancreatic islet cells." (PMID 37006228, 2023). "The neuroendocrine tumor tissue in the liver with VIP expression explains the clinical presentation as Verner-Morrison syndrome and classifies the tumor as a VIPoma." (PMID 33398457, 2021). "VIPoma is an unusual neuroendocrine neoplasm that autonomously secretes VIP." (PMID 32461947, 2020). "The pleiotropic neuropeptide vasoactive intestinal peptide (VIP) is majorly released by neurons and immune cells; however, a special type of neuroendocrine tumor is also able to secrete massive amounts of it." (PMID 33919546, 2021). "The liver lesions are metastases of a neuroendocrine tumor, positive for VIP and synaptophysin, but negative for NKX3.1." (PMID 33398457, 2021).
pulmonary hypertension (15 papers, 2011 to 2023). Increased pressure within the pulmonary circulation due to lung or heart disorder. "VIP deficiency has been suggested to be involved in the development of pulmonary hypertension, with VIP a known neuropeptide causing relaxation of pulmonary vascular smooth muscle cells." (PMID 36085161, 2022). "In addition, VIP attenuates monocrotaline-induced pulmonary hypertension in rats in which NFAT has been implicated in disease pathogenesis." (PMID 28125639, 2017). "Of relevance, genetic deletion of VIP in mice causes not only characteristic hallmarks of chronic airway disease including airway hyperresponsiveness and peribronchial inflammation, but also moderate pulmonary arterial hypertension and considerable pulmonary vascular remodelling." (PMID 24069452, 2013). "As highlighted above, PB1046 is a VIP agonist with sustained release that is being developed for pulmonary hypertension." (PMID 30081920, 2018). "An argument for consequence is derived from studies suggesting a beneficial effect of inhaled VIP on quality of life in COPD, as well as evidence indicating a protective role of VIP against pulmonary hypertension in COPD." (PMID 30081920, 2018). "Previous studies using other compounds to treat pulmonary hypertension in the monocrotaline model including statins, endothelin blockade, rapamycin and vasoactive intestinal peptide have shown that the timing of initiation of therapy is crucial." (PMID 25305681, 2014). "VIP−/− mice have biventricular dilated cardiomyopathy and primary pulmonary hypertension coincidental with strong overexpression of cardiac muscle genes, supporting the important role of VIP in maintaining homeostasis of the heart." (PMID 23700405, 2013). "In monocrotaline-induced pulmonary hypertension in rabbits, VIP dose-dependently decreased pulmonary artery pressure and pulmonary vascular resistance." (PMID 21477377, 2011). "In the present study, we use non-invasive in vivo high resolution magnetic resonance imaging (microMRI) to first test the hypothesis that both the LV and RV are affected in VIP−/− mice, leading to a biventricular dilated cardiomyopathy secondary to pulmonary hypertension." (PMID 23700405, 2013). "VIP appears to act as an endogenous inhibitor of NFAT activity, attenuating pulmonary hypertension." (PMID 28125639, 2017).
somatostatinoma (14 papers, 2015 to 2025). A rare, usually malignant neuroendocrine tumor arizing from delta cells. "Established rare syndromes are caused by vasoactive intestinal peptide (VIP) secretion or somatostatin (somatostatinoma), ACTH (ACTHoma), serotonin (carcinoid syndrome), or PTHrpP (PTHrpP-oma, causing hypercalcemia) secretion." (PMID 37174952, 2023).